GABRB2 (gamma-aminobutyric acid type A receptor subunit beta2)
Diseases named in the same sentence as GABRB2 in open-access papers (continued):
Sharing a sentence is not in itself a finding about the gene and the disease.
progressive supranuclear palsy (1 paper, 2018). A rare late-onset neurodegenerative disease characterized by supranuclear gaze palsy, postural instability, progressive rigidity, and mild dementia. "Interestingly, we found that GABA receptor genes, including GABRB2 and GABRG2, are significantly lower in symptomatic mouse models of tauopathy, as well as in brains with progressive supranuclear palsy." (PMID 30546007, 2018).
tauopathy (1 paper, 2018). Neurodegenerative disorders involving deposition of abnormal tau protein isoforms (tau proteins) in neurons and glial cells in the brain. "To begin to address this question, we examined temporal expression of Gabbr1, Gabrb2, Gabrb3, and Gabrg2 in a mouse model of tauopathy that overexpresses human MAPT p.P301L37." (PMID 30546007, 2018). "The expression of GABA receptor genes, including GABRB2 and GABRG2, were consistently reduced in iPSC-derived neurons and brains from MAPT p.R406W carriers, PSP brains, and mouse models of tauopathy." (PMID 30546007, 2018).
thyroid nodule (1 paper, 2016). A small circumscribed mass in the THYROID GLAND that can be of neoplastic growth or non-neoplastic abnormality. "In the present study, we developed a panel that presents excellent performance in discriminating benign from malignant thyroid nodules by combining only four genes (FN1, GABRB2, NGEF and HMGA2)." (PMID 27793213, 2016).
Ventricular arrhythmia (1 paper, 2024). "This suggests that faster atrioventricular conduction due to Gabrb2 knockout may lead to fatal ventricular arrhythmias." (PMID 38849501, 2024).
ventricular fibrillation (1 paper, 2024). A disorder characterized by an electrocardiographic finding of a rapid grossly irregular ventricular rhythm with marked variability in QRS cycle length, morphology, and amplitude. "In light of this, by intracardiac ECG recordings, we tested the susceptibility of Gabrb2-CKO mice to ventricular tachycardia/ventricular fibrillation (VT/VF)." (PMID 38849501, 2024).
cancer (6 papers, 2020 to 2025). A tumor composed of atypical neoplastic, often pleomorphic cells that invade other tissues. "The frequency of mutation in the GABRA6, GABRA1, and GABRB2 genes was significantly higher than that detected for other cell-cycle- and cell-proliferation-related genes; furthermore, their co-occurrence in patients with cancer was examined." (PMID 39695141, 2024). "Expression of GABRG3, GABRQ, GABRE, and GABRR2 is correlated with inhibition of growth phenotypes in cell lines and with favorable patient outcomes (Broad Institute of MIT & Harvard, firebrowse.org), while expression of other transcripts (GABRB2, GABRP) is associated with cancer progression." (PMID 33187258, 2020). "The fluorescence intensities of ENK and GABRB2 were both reduced in CIBP mice relative to sham mice, suggesting a decrease in inhibitory neurons following cancer cells inoculation (P < 0.05 vs. sham group)." (PMID 40811566, 2025).
tumor (6 papers, 2020 to 2025). "Mainly, the expression profiles of DPP6 and GABRB2 in tumor cases seem to be clearly related with most of the clinical variables under study." (PMID 37372430, 2023). "It was found that GABRB2 and ZMAT3 mRNA expressions are up-regulated in PTC compared to tissue adjacent to the tumor, and that GABRB2 mRNA expression is associated with the best survival in PTC, suggesting its potential usefulness as a prognosis marker." (PMID 37372430, 2023). "Since GABRB2 downregulation inhibits PI3K/AKT activation, DEHP-induced dysregulation of GABRB2 may synergize with T3 receptor mutations to amplify PI3K signaling, accelerating tumor development." (PMID 40900788, 2025). "Apropos tumor stage, it is seen that GABRB2, DPP6 and PTGFR might have some relation with the progression of the disease." (PMID 37372430, 2023). "The results showed that the expression of IPCEF1, TFF3, GLT8D2, TPO and DIO1 were downregulated in the tumor group and DPP4, LRP4, CDH3, KCNJ2, CLDN1, GABRB2, FN1 were upregulated in the tumor group." (PMID 39513122, 2024).
neurological disease (2 papers, 2018 to 2025). "Few studies have evaluated the hypothesis of the genetic interaction of GABRB2 A/C on the interindividual variability of behavioral phenotypes related to a timing error in healthy individuals or in patients with some neurological disease." (PMID 30086746, 2018).
infection (1 paper, 2021). The state of being infected such as from the introduction of a foreign agent such as serum, vaccine, antigenic substance or organism. "In contrast, infection of conditional shRNA AAV9 against Gabrb2 and Gabra4 attenuated the decline in body temperature of miR-33f/fDBH-Cre mice at a level equal to or greater than that of miR-33f/f mice." (PMID 33594062, 2021).
movement disorder (1 paper, 2024). Neurological conditions resulting in abnormal voluntary or involuntary movement, which may impact the speed, fluency, quality and ease of movement. "Such movement disorders have previously been reported in individuals with GABRB2 variants, and we demonstrate that they are strongly linked to GOF-associated disorders." (PMID 38996765, 2024). "Importantly, the mechanisms underlying this phenotypic diversity and risks of developing severe co-morbidities such as the prominent movement disorders associated with GABRB2, are unclear." (PMID 38996765, 2024).
GABRB2 also shares sentences with these, for which no sentence is quoted: Intellectual disability (6 papers); bipolar disorder (4); cognitive deficits (3); microcephaly (3); autism (2); breast carcinoma (2); neurodevelopmental disorder (2); ) dependence (1); Angelman syndrome (1); Arrhythmia (1); Athetosis (1); attention deficit-hyperactivity disorder (1); autism spectrum disorder (1); AV block (1); Chorea (1); colorectal cancer (1); Delusion (1); developmental and epileptic encephalopathy (1); Dyskinesia (1); Dystonia (1); Encephalopathy (1); fibromyalgia (1); generalized anxiety disorder (1); glioblastoma (1); glioma (1); Hallucinations (1); Hypotonia (1); idiopathic generalized epilepsy (1); infantile spasms (1); kidney tumors (1).
A further 8 diseases each share a sentence with GABRB2 in 1 paper.